DNA2 (DNA replication helicase/nuclease 2)
Diseases named in the same sentence as DNA2 in open-access papers (continued):
Sharing a sentence is not in itself a finding about the gene and the disease.
colorectal cancer (2 papers, 2018 to 2021). A primary or metastatic malignant neoplasm that affects the colon or rectum. "In support of this notion, elevated DNA2 levels have been shown to correlate with a poor prognosis for breast cancer patients and stemness of cancerous cells in colorectal cancer." (PMID 33924313, 2021). "On the other hand, DNA2 amplification and over-expression has been reported for a range of cancers including breast, pancreatic, and colorectal cancer." (PMID 33924313, 2021).
congenital myopathy (2 papers, 2019 to 2020).
glioma (2 papers, 2024 to 2025). A benign or malignant brain and spinal cord tumor that arises from glial cells (astrocytes, oligodendrocytes, ependymal cells). "The influence of certain genes, such as DNA2, EGFR, FAIM, and HEATR3, on glioma risk, which is mediated through alterations in telomere length, enhances the elucidation of pathogenic mechanisms and introduces novel strategies for targeting telomere‐related pathways." (PMID 39722126, 2024). "Additionally, it was observed that the mediation effects of DNA2 and HEATR3 via telomere length were in the opposite direction to their respective total effects, suggesting a potential masking effect, wherein these genes may diminish part of the glioma risk effect size by reducing telomere length." (PMID 39722126, 2024).
multiple myeloma (2 papers, 2021 to 2024). "In myeloma, ILF2 antisense oligonucleotide (Interleukin Enhancer Binding Factor, a key modulator of the DNA repair pathway) is a synthetic lethal target with DNA2 (DNA replication helicase/nuclease 2)." (PMID 34359720, 2021).
acute myeloid leukemia (1 paper, 2023). Acute myeloid leukemia (AML) is a group of neoplasms arising from precursor cells committed to the myeloid cell-line differentiation. "According to TCGA Pan-Cancer database, DNA2 mRNA expression is upregulated in many types of cancer including acute myeloid leukemia, bladder, breast, colon, esophageal, lung, ovarian, rectal, stomach, and uterine cancers, etc.." (PMID 37756561, 2023).
adenoma (1 paper, 2020). A neoplasm arising from the epithelium. "Comparing of corresponding adenomas, the expressions of BUB1, BUB1B, PLK4, and DNA2 in carcinomas were higher." (PMID 33134313, 2020).
bone osteosarcoma (1 paper, 2018). A usually aggressive malignant bone-forming mesenchymal neoplasm arising from the bone. "NSC 105808 negatively affected proliferation of human bone osteosarcoma U2OS cells, and its anti-proliferative effect was suppressed by ectopic expression of DNA2 at a level 1.5–2.0-fold greater than endogenous DNA2, leaving the authors to propose that DNA2 is the target of the compound." (PMID 29998112, 2018).
chronic pancreatitis (1 paper, 2017). A chronic inflammatory process causing damage and fibrosis of the pancreatic parenchyma. "Moreover, patients with chronic pancreatitis expressed DNA2 at an elevated level in their pancreatic tissue." (PMID 28414320, 2017).
colorectal adenocarcinoma (1 paper, 2020). The most common type of colorectal carcinoma. "In order to rule out any cell line-specific effects, we next sought to validate CHK1 and DNA2 in two additional cell lines, namely U2OS (human osteosarcoma) and DLD-1 (colorectal adenocarcinoma)." (PMID 32542389, 2020).
deafness (1 paper, 2022). An inherited or acquired condition characterized by the complete loss of the ability to hear from one or both ears. "Interestingly, DNA2-related deafness has not been previously reported, which might be explained by sufficient energy supplementation in those cases." (PMID 36064591, 2022).
endometriosis (1 paper, 2021). The growth of functional endometrial tissue in anatomic sites outside the uterine body. "Together, these data suggest that both CHK1 and DNA2, two key players in DNA damage repair, were upregulated in endometriosis samples." (PMID 34047877, 2021). "In the present study, we propose that DNA replication ATP-dependent helicase/nuclease 2 (DNA2) might be upregulated in endometriosis." (PMID 34047877, 2021). "The next step will be to discover and test DNA2 inhibitors both in vitro and in vivo, which could be invaluable for endometriosis therapy either alone or in combination with other established strategies." (PMID 34047877, 2021). "Interestingly, EMSCs from patients with endometriosis were sensitive to E2 treatment, resulting in a 1.5–2-fold increase in DNA2 mRNA expression and 1.2–2.8-folds increase in CHK1 mRNA levels." (PMID 34047877, 2021). "Taken together, our study demonstrated the overexpression of DNA2 in human endometriosis, which might be responsible for the upregulated cell proliferation and migration." (PMID 34047877, 2021). "In this study we sought to determine whether DNA2 is involved in endometriosis." (PMID 34047877, 2021).
epilepsy (1 paper, 2024). A brain disorder characterized by episodes of abnormally increased neuronal discharge resulting in transient episodes of sensory or motor neurological dysfunction, or psychic dysfunction. "And cell-based assays illustrated the possible mechanism of DNA2 regulated epilepsy: DNA2 depletion caused accumulated mitochondrial DNA damage, affecting mitochondrial oxidative phosphorylation and ATP production." (PMID 38802339, 2024). "Our study is the first to identify the DNA2 variant (pR592*) in the hippocampal tissue of MTLE patients, and moreover, we explored the possible mechanism underlying the involvement of DNA2 in epilepsy." (PMID 38802339, 2024). "Considering that about 40–50% of the ATP generated by the mitochondria are consumed by Na+, K+-ATPase to maintain Na+/K+ equilibrium and cell excitability, we sought to examine the association among DNA2 deletion, Na+, K+-ATPase activity and epilepsy in cells." (PMID 38802339, 2024). "In summary, DNA2 loss affected the development and behaviors of zebrafish, especially neuroelectrophysiological of zebrafish, which further proved the key role of DNA2 played in epilepsy." (PMID 38802339, 2024). "These disorders caused by DNA2 dysfunction are important causes of epilepsy." (PMID 38802339, 2024). "In summary, DNA2 mutations are frequently reported with neuromuscular disease, little is known about the role of DNA2 in central nervous system, especially in epilepsy." (PMID 38802339, 2024). "In summary, we are the first to report the pathogenic somatic mutation of DNA2 gene in the patients with MTLE disease, and we uncovered the mechanism of DNA2 regulating the epilepsy." (PMID 38802339, 2024). "Next, we wanted to explore the pathway of DNA2 absence regulating epilepsy." (PMID 38802339, 2024). "In conclusion, we provide mechanisms by which DNA2 regulate cell excitability and epilepsy." (PMID 38802339, 2024). "Our results indicated that DNA2 absence regulated cell membrane potential and cell growth through regulating ATP generation by mitochondrial oxidative phosphorylation and Na+, K+-ATPase activity, thus getting involved in epilepsy." (PMID 38802339, 2024).
External ophthalmoplegia (1 paper, 2022). Paralysis of the external ocular muscles. "DNA2 may play roles in mtDNA replication, and the deletions of mtDNA lead to progressive external ophthalmoplegia." (PMID 35456484, 2022).
gastric cancer (1 paper, 2020). A primary or metastatic malignant neoplasm involving the stomach. "DNA2 deficiency and DNA2 mutations have been linked to human cancers, including gastric cancer." (PMID 31754720, 2020).
hepatocellular carcinoma (1 paper, 2025). A malignant tumor that arises from hepatocytes. "The results showed that MY019(FC ≈ 2.0), DNA2(FC ≈ 2.3) and FDPS(FC ≈ 1.9) were significantly highly expressed in the human hepatocellular carcinoma cell line Hep3B2.1-7 compared to LO2 in normal human hepatocytes (P < 0.05)." (PMID 40839681, 2025).
high blood pressure (1 paper, 2014). "This list included Angptl7, Hdc, Cndp2, Dna2, Edn3, which were up-regulated in the hypertensive mice and may have a physiological role in the regulation of high blood pressure." (PMID 25259444, 2014).
lung carcinoma (1 paper, 2023). "Among these compounds, d16 was identified and proved to be a more potent DNA2 inhibitor than C5 in blocking cell proliferation of various cancer types including ovarian, breast, cervical, and lung cancers." (PMID 37756561, 2023).
lung squamous cell carcinoma (1 paper, 2023). "The expression of DNA2 protein is correlated with DNA2 mRNA in lung squamous cell carcinoma." (PMID 37756561, 2023).
Majewski syndrome (1 paper, 2025). "Endocrine dysfunction, well reported in XRCC4-related MPD, is also observed in other DNA repair defects, including DNA2, BLM, NSMCE2-related MPD [MIM#615807, MIM#210900, MIM#617253], but also in other MPD such as Majewski syndrome." (PMID 40114033, 2025).
myasthenia (1 paper, 2024). "Recent years, DNA2 gene mutations were discovered to be closely associated with progressive myasthenia and various neoplastic lesions." (PMID 38802339, 2024).
ovarian tumors (1 paper, 2023). "High DNA2 expression is associated with shorter progression-free survival in ovarian tumors, regardless of tumor stage or grade." (PMID 37756561, 2023).
cancer (43 papers, 2014 to 2026). A tumor composed of atypical neoplastic, often pleomorphic cells that invade other tissues. "DNA2 coordinates essential maintenance processes, including cell-cycle progression; however, its aberrant activity has been implicated in cancer cell survival under oncogene-induced replication stress." (PMID 42307783, 2026). "We show that DNA2 gene deficiency or treatment with a DNA2 inhibitor results in G4 accumulation in MEFs and various human cancer cells." (PMID 40330857, 2025). "As a result, Dna2-deficient mice develop aneuploidy-associated cancers and have dysfunctional telomeres." (PMID 36032672, 2022). "These activities are necessary to promote genome integrity in normal cells, as functional deficiency of DNA2 has been shown to cause genome instability and promote cancer initiation in mammals." (PMID 31754720, 2020). "DNA2 gene mutations in estrogen-dependent cancers are concentrated in the helicase and nuclease structures." (PMID 31319533, 2019). "The amount of Dna2 in cells also seems to be important as dna2∆/DNA2 heterozygous mice show increased levels of aneuploidy-associated cancers and cells from these mice contain high numbers of anaphase bridges and dysfunctional telomeres." (PMID 29559500, 2018). "Many cancers are associated with oncogene activation, which can result in replication stress, and DNA2 plays an important role in cellular defense against this stress." (PMID 28718810, 2017). "This enhanced DNA2 expression was associated with increased genomic instability typical for almost all cancer cells." (PMID 28718810, 2017). "This suggests that the cancer-related mutations in DNA2 lead to inactivation or impairment of DNA2 activity, which is known to be essential for the maintenance of genomic stability." (PMID 25238049, 2014). "All these data support a role for DNA2 in cancer etiology and indicate that DNA2 mutations and functional deficiency may serve to promote cancer development." (PMID 31754720, 2020). "Furthermore DNA2 mutations have been linked to cancers, as well as developmental and mitochondrial disorders." (PMID 31754720, 2020). "Overexpression of DNA2 is frequent in cancer cells and has been linked to poor patient prognosis." (PMID 32544229, 2020). "As elevated replication stress is a hallmark of cancer cells, increased DNA2 expression might help tumor cells overcome this barrier." (PMID 31098407, 2019). "It is tempting to speculate that even germline inherited DNA2 mutations might predispose to cancer, as suggested by the high incidence of different forms of neoplasia in Patient 1’s paternal relatives." (PMID 31478350, 2019). "Indeed, several groups have reported that DNA2 depletion by RNA interference causes the reduced proliferation of cancer cells." (PMID 29998112, 2018). "This suggests a complex role in cancer, where genome instability caused by impaired DNA2 function may drive tumorigenesis, whereas upregulation of DNA2 may help cancer cells to survive continuous DNA replication stress." (PMID 27779184, 2016). "In order to gain insight into how these mutations contribute to cancer development, we developed a system in yeast to determine whether these mutations abrogate DNA2 activity." (PMID 25238049, 2014). "Higher expression levels of DNA2 in tumor cells may attenuate the replication stress and DNA damage accumulation associated with cancer." (PMID 25238049, 2014). "However, humans and mice heterozygous for DNA2 null mutations are viable, due to partially compensating pathways, suggesting that a therapeutic window can be found for DNA2 inhibition, particularly in cancers that overexpress DNA2." (PMID 31754720, 2020). "It is also implicated that the high expression of DNA2 may promote the cancer cells proliferation." (PMID 31252692, 2019). "DNA2 may therefore be implicated in cancer development in a multifaceted manner." (PMID 25238049, 2014).
cancer (continued). "DNA2 nuclease is commonly overexpressed in various cancer types, and this elevated level of DNA2 is often essential for the survival of cancer cells." (PMID 39673516, 2024). "Our functional data revealed a different role of DNA2 in cancer cells and demonstrated that DNA2 is essential to maintaining MM cells’ survival under DNA damage-induced metabolic reprogramming." (PMID 38331987, 2024). "DNA2 is overexpressed in cancer cells, and its overexpression in yeast results in telomere dysfunction." (PMID 39082275, 2024). "Data mining analysis assessing the clinical significance of DNA2 across TCGA human cancer types shows that DNA2 expression is upregulated in many types of cancer." (PMID 37756561, 2023). "Answering this question is essential to understanding how both FANCD2 and DNA2 are involved in fork protection and maintenance of genome stability and thus understanding their roles in cancer development and treatment." (PMID 37526271, 2023). "In fact, there is extensive evidence that over-expression of DNA2 in cancer cells correlates with poor prognosis." (PMID 37526271, 2023). "Our results indicate new directions for experiments in resolving the role of DNA2 in these various processes and their relative significance to cell viability and cancer." (PMID 37526271, 2023). "It has been reported that the mutations in DNA2, ACO2, and ATP7A were correlated with the initiation or poor clinical outcomes of cancers." (PMID 36685880, 2022). "DNA2+/− mice exhibit genome instability and a higher incidence of cancer, suggesting that DNA2 haploinsufficiency drives malignant transformation." (PMID 33924313, 2021). "Research also found that chemical inhibition of DNA2 selectively attenuated the growth of various cancer cells." (PMID 33574966, 2021). "Being a crucial player at stalled RFs, DNA2 is a promising target for anti-cancer therapy aimed at eliminating cancer cells by replication-stress overload." (PMID 33924313, 2021). "DNA2 is reported upregulated in several cancer types and facilitates homologous recombination to repair replication-associated DNA DSBs, thereby providing cancer cells with survival advantages under replication stress." (PMID 33574966, 2021). "Tissue expression was confirmed to be significantly different in cancer vs. control samples for DNA2, MAOA, PARP1, TYR, and HDAC1 in the IST Online database and for PTK2B, MAOA, PARP1, and TYR in the GEPIA2 database." (PMID 34199192, 2021). "Thus, DNA2 mutations or functional deficiency may lead to cancer initiation." (PMID 31754720, 2020). "Both CHK1 and DNA2 are key players in DNA damage repair and represent potential therapeutic targets for cancer therapy." (PMID 32542389, 2020). "Elevated levels of DNA2 mRNA were also found in a wide range of cancer types, further demonstrating the importance of DNA2-mediated recovery of stalled forks in replication stress tolerance." (PMID 32432041, 2020). "In cancer, on the other hand, DNA2 is frequently overexpressed, potentially reflecting an adaptation to endogenous RS and elevated levels of RF stalling." (PMID 30893921, 2019). "In several different cancer cell models, the DNA2 inhibitor suppressed proliferation of cancer cells with oncogene-induced replication stress, suggesting a potential avenue of further exploration for cancer therapy." (PMID 29998112, 2018). "Of those tested in cell-based assays, small molecule inhibitors of DNA unwinding catalyzed by WRN, BLM, and DNA2 all negatively affect proliferation of cancer cells and induce DNA damage and/or chromosomal instability." (PMID 29998112, 2018). "Similar to genetic ablation of DNA2, chemical inhibition of DNA2 selectively attenuates the growth of various cancer cells with oncogene-induced replication stress." (PMID 28414320, 2017).